MAPK8 (mitogen-activated protein kinase 8)
Diseases named in the same sentence as MAPK8 in open-access papers (continued):
Sharing a sentence is not in itself a finding about the gene and the disease.
tumor (continued). "In summary, our study demonstrates that menadione, an FDA-approved compound, exerts potent anti-tumor effects in CRC cells by simultaneously inducing necroptosis, apoptosis, and autophagy, which is mediated through activation of MAPK8." (PMID 40872536, 2025). "However, MAPK8 not only exerts pro-carcinogenic effects but may also mediate tumor suppression." (PMID 40369663, 2025). "Several critical proteins in tumor development and progression, such as PTEN, MAPK8, CUL1, and RAC3, were enriched." (PMID 35990607, 2022). "The MAPK8 gene, also known as JNK1, is related to tumor cell survival by controlling autophagy by phosphorylation of the antiapoptotic protein BCL-2." (PMID 33316872, 2020). "The higher expression of MAPK8 is correlated to the lower tumor recurrence for HCC patients, and upregulation of MAPK8 could inhibit the proliferation, migration, and invasion abilities of mouse HCC cell lines." (PMID 36133813, 2022). "Furthermore, four genes (MAP2K1, EIF4EBP1, MAPK8, and RPS6KB1) were enriched in ERBB signaling pathway, required for GBM stem cell proliferation, and three genes (MAP2K1, MAPK8, and RPS6KB1) were enriched in NFAT pathway, promoting tumor angiogenesis." (PMID 28056026, 2017). "Several published studies showed that TLR9 signaling could induce the activation of JNK(mitogen-activated protein kinase 8) and p38 MAPK (mitogen-activated protein kinases) pathway to enhance tumor growth." (PMID 26087186, 2015). "Several tumor-related genes such as ERO1L, ITGA3, and MAPK8 were found closest to LOXL2-e13." (PMID 25254241, 2014). "There was a notable divergence in gene expression levels between neoplastic and neighboring tissues, with genes such as BRCA1, CHEK2, and IKBKE substantially amplified in tumor tissues, while genes such as ZMYND11, MAPK8, and RPS3 exhibited notable elevation in adjacent nontumor tissues." (PMID 41497799, 2025). "NR2C2, MAPK8, PPARA, and PTGS2 are all downregulated in tumor versus normal tissues." (PMID 35814450, 2022).
infection (294 papers, 2004 to 2026). The state of being infected such as from the introduction of a foreign agent such as serum, vaccine, antigenic substance or organism. "Pathway analysis of regulated phosphoproteins revealed several kinase-mediated signaling pathways (AKT1, PRKACA, and JNK1) being altered during JEV infection, with JNK1 (MAPK8) substrates significantly overrepresented during infection." (PMID 34696709, 2021). "In our analysis, genes coding JNK (MAPK8), c-Jun (JUN), and c-Fos (FOS) were all implicated in the subnetwork from the chronic stage of infection, and all showed significantly increased transcript expression levels at this stage." (PMID 28487699, 2017). "At 24 h after infection, the following genes were upregulated in infected macrophages transfected with the let-7e inhibitor compared to macrophages transfected with NC: Tlr7, Ly96/MD-2, Casp8, Map3k1, Mapk8, Ptgs2/Cox2, Csf 3/GCSF, and the ubiquitin-conjugating enzyme E2N (Ube2n)." (PMID 30555476, 2018). "The genes IKBKB, IRAK3, IRF5, MAP2K4 (MEK4), MAPK14 (p38), MAPK8 (JNK1) and NFKB1 (p50) were upregulated not only in both cell types, but also after infection with whole bacteria of P. gingivalis W83 as well as with the membrane fraction." (PMID 28056810, 2017). "MAPK8, also known as Jnk-1 and a member of the Jnk family of kinases, is activated via Wnt/PCP receptor signaling when cells are exposed to inflammation, oxidative stress, DNA damage, osmotic stress, infection, or cytoskeletal changes." (PMID 39000054, 2024). "The up-regulation of MAPK8 and PTI4 genes in HB than in GM suggests that the activation of their transcript in the resistant cultivar may not be necessarily dependent on active pathogenesis as occurred during infection at the early stage of tuberization." (PMID 32673321, 2020). "Using an overexpression experiment, Fung showed that JNK/MAPK8 participated in coronavirus–host interaction, so silencing lncRNA−MSTRG.16919.1 may affect the expression of SKIV2L2, JAK2, PIK3CB and MAPK8 proteins and then regulate the infection of MDBK cells by BHV−1." (PMID 36298658, 2022). "Interestingly, by day 7 of infection, multiple genes were elevated in young H1N1 infected lung, such as Atg5, Mapk8, Tbk1, Casp8, and Ripk1, that were not similarly expressed in response to H3N2." (PMID 34829979, 2021).
bacterial infection (36 papers, 2008 to 2026). "Interestingly, more antibacteria genes were also upregulated at 4 dpi in the nose when compared to that of the pharynx, in which only three genes (SAA, galectin, and MAPK8) were upregulated at 4 dpi, suggesting that viral invasion could lead to secondary bacterial infection." (PMID 34804060, 2021).
connective tissue disorder (5 papers, 2020 to 2023). A disease involving the connective tissue. "Interestingly, JNK1-deficient patients with CMC were also found to have a novel connective tissue disease, thus distinguishing mutant MAPK8 from other monogenic inducers." (PMID 33178226, 2020). "Indeed, mono- or biallelic deleterious variants of IL17F, IL17RA, IL17RC, and TRAF3IP2 (encoding ACT1) have been detected in patients with isolated CMC, and MAPK8 has been identified in patients with both CMC and a connective tissue disorder." (PMID 37577484, 2023).
MAPK8 also shares sentences with these, for which no sentence is quoted: Hyperglycemia (84 papers); Cerebral ischemia (73); neurodegenerative disease (69); liver fibrosis (64); liver cancer (48); Parkinson disease (46); colitis (45); Cognitive impairment (44); rheumatoid arthritis (40); ischemic stroke (38); metabolic disorders (36); cardiovascular diseases (35); injury (34); Arthritis (31); lung adenocarcinoma (31); pulmonary fibrosis (30); heart failure (28); renal fibrosis (27); kidney disease (25); lymphoma (25); Glucose intolerance (23); nasopharyngeal carcinoma (23); osteoarthritis (23); endothelial dysfunction (22); immune deficiency (22); Myocardial fibrosis (22); neurological disorders (22); inflammation (21); liver diseases (20); glaucoma (19).
A further 543 diseases each share a sentence with MAPK8 in 19 papers or fewer.